BIK (BCL2 interacting killer)
Diseases named in the same sentence as BIK in open-access papers (continued):
Sharing a sentence is not in itself a finding about the gene and the disease.
lymphoma (3 papers, 2013 to 2021). A malignant (clonal) proliferation of B- lymphocytes or T- lymphocytes which involves the lymph nodes, bone marrow and/or extranodal sites. "In head and neck squamous cell carcinoma cells, increased BIK by Bortezomib enhanced cisplatin-induced apoptosis and loss of Bik accelerated murine lymphoma development or rendered lymphoma cells resistant to DNA damaging drugs." (PMID 30176890, 2018). "BIK inactivation in a mutational manner is observed in lymphomas, but epigenetic modification seems to be also implicated in BIK silencing in other cancers as Multiple Myeloma." (PMID 24709797, 2013). "Importantly, in our GWAS, which was also adjusted for white blood cell counts, we found association signals near genes involved in leukaemia and lymphoma development (CRK, BAK1, CDK6, MDFIC, BIK) as well as a significant enrichment of pathways related to immune cell proliferation." (PMID 33385171, 2021).
melanoma (3 papers, 2019 to 2025). A malignant, usually aggressive tumor composed of atypical, neoplastic melanocytes. "This was associated with an insignificant effect of AG on BIK transcript level in all melanoma cell lines (Online Resource 5b)." (PMID 30989459, 2019). "Pro-apoptotic BIK expression mediated apoptosis induction in BRAFV600E-mutant M14 melanoma cell clones responding to vemurafenib and trametinib therapy." (PMID 39935431, 2025). "Moreover, some apoptosis-related proteins have been associated with melanoma sensitivity to BRAF and MEK inhibitors, such as the Bcl2-interacting killer (BIK) protein that mediates on BRAF inhibitor effectiveness and Survivin that contributes to melanoma cells survival by inhibiting apoptosis." (PMID 36358912, 2022).
Alzheimer disease (2 papers, 2018 to 2022). A progressive, neurodegenerative disease characterized by loss of function and death of nerve cells in several areas of the brain leading to loss of cognitive function such as memory and language. "For example, RHBDD1 is an important protease and cleaves several different substrates, including BIK, a proapoptotic member of the Bcl-2 family, and the amyloid precursor protein, a key molecule in the etiology of Alzheimer disease." (PMID 30286765, 2018). "For example, apoptosis of neurons during Alzheimer's disease progression could be induced by PGD2 which stimulated expression of BIK and suppressed expression of ARRB1." (PMID 33683530, 2022).
Cerebral ischemia (2 papers, 2021 to 2022). Restriction of arterial blood supply to the brain associated with insufficient oxygenation to support the metabolic requirements of the tissue. "Previously, miR-1306-5p overexpression has been indicated to alleviate injury caused by cerebral ischemia/reperfusion in vitro by targeting BIK." (PMID 34517787, 2021). "Recently, a study found that Up-regulation of miR-1306 to lower cerebral ischemia/reperfusion injury in vitro by targeting BIK." (PMID 36212145, 2022).
cholangiocarcinoma (2 papers, 2020 to 2025). A carcinoma that arises from the intrahepatic biliary tree (intrahepatic cholangiocarcinoma) or from the junction, or adjacent to the junction, of the right and left hepatic ducts (hilar cholangiocarcinoma). "In the present study BIK was highly expressed in the high-risk patients, and we hypothesized that this might be related to the adaptation of cholangiocarcinoma cells to BIK-mediated apoptosis." (PMID 40438322, 2025). "For instance, p27KIP1 and BIK have been extensively studied, and were reported to modulate the chemosensitivity in malignant glioma, cholangiocarcinoma, and breast cancer." (PMID 32826865, 2020).
malignant glioma (2 papers, 2020 to 2021). A grade III or grade IV glioma arising from the central nervous system. "Interestingly, together with CST6, the apoptosis-inducer Bcl-2-interacting killer (BIK) is also a target of epigenetic silencing in malignant gliomas." (PMID 33919854, 2021).
neuroblastoma (2 papers, 2022). Neuroblastoma (NB) is the most common solid, extracranial childhood tumor. "MiR-1306-5p was downregulated in neuroblastoma cells (SH-SY5Y) induced by oxygen glucose deprivation by targeting Bcl2-interacting killer (BIK), but it was not largely reported in other diseases." (PMID 34582743, 2022).
acute myeloid leukemia (1 paper, 2016). Acute myeloid leukemia (AML) is a group of neoplasms arising from precursor cells committed to the myeloid cell-line differentiation. "In acute myeloid leukemia, BIK was found to be upregulated in the leukemic cells compared to controls." (PMID 27902785, 2016).
Burkitt lymphoma (1 paper, 2022). A rare form of malignant mature B-cell non-Hodgkin lymphoma. "Small studies predominantly limited to Burkitt lymphoma (BL) cell lines suggest TGFB may regulate the expression of apoptotic regulators BIK and Bcl-xL." (PMID 35406544, 2022).
esophageal adenocarcinoma (1 paper, 2020). A malignant tumor with glandular differentiation arising predominantly from Barrett mucosa in the lower third of the esophagus. "The statistically higher expressions of PLAUR, BIK, DRAM2, RNF41, STK38, ATG5, and PARP1 were measured in esophageal cancer than those in normal tissue, while statistically significant differences were also detected between ESCC and esophageal adenocarcinoma (EAC)." (PMID 32974198, 2020).
Ewing sarcoma (1 paper, 2020). A small round cell tumor that lacks morphologic, immunohistochemical, and electron microscopic evidence of neuroectodermal differentiation. "However, in Ewing sarcoma cells, no appreciable levels of BIK protein are detectable even in the presence of the proteasome inhibitor MG132, and FATE1 depletion does not induce BIK accumulation." (PMID 32486221, 2020).
HIV-1 infection (1 paper, 2025). The type species of lentivirus and the etiologic agent of acquired immunodeficiency syndrome (AIDS). "Furthermore, SAMHD1-enhanced apoptosis was associated with increased BIK expression, and BIK contributed to SAMHD1-enhanced apoptosis during HIV-1 infection." (PMID 40434097, 2025). "The reduced BIK protein level in SAMHD1 KO cells might have failed the required threshold for BIK protein to trigger apoptosis for HIV-1 infection in THP-1 cells." (PMID 40434097, 2025). "Furthermore, SAMHD1-enhanced apoptosis is linked to elevated levels of the pro-apoptotic protein BCL-2-interacting killer (BIK) in cells, which contributes to enhanced apoptosis during HIV-1 infection." (PMID 40434097, 2025). "Therefore, other cellular factors and mechanisms might be involved in SAMHD1/BIK-dependent mitochondrial apoptosis induced by HIV-1 infection." (PMID 40434097, 2025). "To investigate the role of BIK in SAMHD1-enhanced apoptosis, we knocked out BIK expression in THP-1 SAMHD1 Ctrl and SAMHD1 KO cell lines and then measured HIV-1 infection and apoptosis." (PMID 40434097, 2025). "HIV-1 infection of SAMHD1-expressing THP-1 cells did not further promote BIK protein expression by 4 dpi, at which SAMHD1-enhanced apoptosis was already observed." (PMID 40434097, 2025). "Loss of BIK expression reverted Δψm in SAMHD1-expressing THP-1 cells, but not in SAMHD1 KO cells, upon HIV-1 infection, suggesting that BIK is required for SAMHD1-enhanced mitochondrial depolarization by HIV-1." (PMID 40434097, 2025). "Interestingly, BIK expression was increased by HIV-1 infection at 8 dpi only in THP-1 Ctrl cells but not in SAMHD1 KO cells based on the average of three independent experiments." (PMID 40434097, 2025).
influenza (1 paper, 2025). An acute viral infection of the respiratory tract, occurring in isolated cases, in epidemics, or in pandemics; it is caused by serologically different strains of viruses (influenzaviruses) designated A, B, and C, has a 3-day incubation period, and usually lasts for 3 to 10 days. "The association of the promoter BIK SNP, shown to alter BIK expression levels, with severity of influenza-caused disease symptoms in humans supports the effect of BIK on viral replication in the AECs." (PMID 40627391, 2025). "Chi-squared comparison of AA vs. AG/GG showed that the AA allele of BIK SNP is significantly associated with severe influenza as defined by the total symptom score (P = 0.0002)." (PMID 40627391, 2025). "BIK SNP’s association with influenza severity reveals host genetic risk factors, suggesting its use as a screening marker for personalized treatment." (PMID 40627391, 2025). "Since viral replication and protein levels were increased in NHBEA/A compared with NHBEG/G, we investigated whether the BIK SNP that affects its expression is associated with influenza disease severity." (PMID 40627391, 2025). "Critically, the AA variant, associated with elevated BIK, correlates with severe influenza." (PMID 40627391, 2025). "Critically, a genetic variation (rs738276) in the BIK gene, influencing BIK expression, correlates with altered viral replication in air–liquid interface differentiated primary normal human bronchial epithelial cells and influenza severity in humans." (PMID 40627391, 2025). "The genetic link between BIK expression and human influenza outcomes, coupled with the BIK/NP interaction, highlights BIK and β5 as promising targets for novel antiviral therapies." (PMID 40627391, 2025). "Furthermore, we show that genetic variation in BIK affects viral replication in the airway epithelial cells and correlates with human influenza severity." (PMID 40627391, 2025). "Our findings uncover an IAV–BIK–β5 axis that governs viral replication, suggesting that targeting BIK or β5 may offer therapeutic strategies against influenza." (PMID 40627391, 2025). "We investigated the role of Bcl-2-interacting killer (BIK) in IAV infection using cellular and mouse models, and influenza-infected human cohort." (PMID 40627391, 2025).
microphthalmia (1 paper, 2024). Congenital or developmental anomaly in which the eyeballs are abnormally small. "Further upstream of the caspases in the apoptosis pathway, XAF1 (LFC +5.26, p < 0.0001), IRF1 (LFC +1.53, p < 0.000341), and STAT1 (LFC +1.850, p < 0.000000118) and pro-apoptotic genes BIRC3 (LFC +2.39, p < 0.00000695) and BIK (LFC +1.43, p < 0.00178) was upregulated in microphthalmia patients." (PMID 38821055, 2024).
osteoporosis (1 paper, 2024). A condition of reduced bone mass, with decreased cortical thickness and a decrease in the number and size of the trabeculae of cancellous bone (but normal chemical composition), resulting in increased fracture incidence. "To address these deficiencies, we intend to conduct animal studies to enhance the reliability of the biomarkers and will continue monitoring the progress of ACAA2, DAP3, and BIK in relation to osteoporosis." (PMID 39130750, 2024).
ovarian tumours (1 paper, 2016). "Supporting a clinically meaningful role for LARP1 in the post-transcriptional regulation of BCL2 and possibly also BIK expression in ovarian malignancies, expression of LARP1 positively correlates with BCL2, but is negatively correlated with BIK expression in a study of over 400 ovarian tumours." (PMID 26717985, 2016).
pancreatic cancer (1 paper, 2022). "We showed that EXOSC4 regulates the stability of SESN2 mRNA in pancreatic cancer cells; however, we were unable to evaluate the effects of EXOSC4 on BIK mRNA because of their low expression levels." (PMID 35008922, 2022). "We concluded that EXSOC4 downregulates BIK mRNA and destabilizes SESN2 mRNA in pancreatic cancer cells." (PMID 35008922, 2022). "We concluded that EXOSC4-mediated downregulation of BIK and SESN2 is required for the proliferation of pancreatic cancer cells." (PMID 35008922, 2022). "Although EXOSC4 regulates the expression of BIK and SESN2 mRNA in pancreatic cancer cells, how EXOSC4 recognizes the mRNAs is still unclear." (PMID 35008922, 2022). "Our study provides evidence for EXOSC4-mediated regulation of BIK and SESN2 mRNA in the survival of pancreatic tumor cells." (PMID 35008922, 2022). "Furthermore, EXOSC4 knockdown increased mRNA levels of BIK and SESN2, which regulate apoptosis in pancreatic cancer cells." (PMID 35008922, 2022). "Since EXOSC4 is localized in the nucleus of pancreatic cancer cells, EXOSC4 may regulate BIK expression via not only mRNA stability but also transcriptional regulation." (PMID 35008922, 2022). "Furthermore, we revealed that EXOSC4 knockdown induces BIK and SESN2 mRNA levels in pancreatic cancer cells." (PMID 35008922, 2022). "We speculate that EXOSC4 knockdown leads to the reduction in the growth of pancreatic tumor cells by upregulation of SESN2 and BIK mRNA." (PMID 35008922, 2022).
retinoblastoma (1 paper, 2015). A malignant tumor that originates in the nuclear layer of the retina. "Instead, Caspase-8 and BIK are methylated in the Wery Rb1 cell line, thus implying that up-regulation is due to a direct effect of the agent on the genes (SM MSP Wery cells file), and justifying transcriptional activation and sensitization to apoptosis of retinoblastoma cells." (PMID 26143641, 2015).
Sézary syndrome (1 paper, 2016). "In regard to molecular mechanisms of TCF3 antitumor effects, in Sézary syndrome (a subtype of T cell lymphoma) derived cells, no significant cell death induction was observed after E47 overexpression, whereas, up-regulation of proapoptotic genes including BCL2L11 and BIK have been seen." (PMID 27166193, 2016).
T cell lymphoma (1 paper, 2016). "BIK has also been reported to be upregulated upon over-expression of E47 in T cell lymphoma and in a murine TCF3/E2A-deficient hematopoietic progenitor cell line." (PMID 27166193, 2016).
tumor (35 papers, 2005 to 2025). "As shown by western blot using the lysates from tumor xenografts, the observed inhibition of tumor was probably caused by the BIK-mediated cell apoptosis." (PMID 28151486, 2017). "By increasing histone acetylation, martinostat can restore pro-apoptotic factors (e.g., BAD and BIK) and tumor suppressors (e.g., PTEN), suppress pro-survival genes, and restore critical pathways." (PMID 40671124, 2025). "The second tumor suppressor, BIK, belongs to the proapoptotic BH3-only family of proteins that are upregulated in response to various stress signals and act as antagonists of prosurvival proteins." (PMID 37728212, 2023). "BIK functions as a pro-apoptotic tumor suppressor in several human cancers and its expression in cancer is downregulated by chromosomal deletion or transcriptional silencing." (PMID 35008922, 2022). "Both, proapoptotic BCL-2 or MAP kinase pathway members (BIK, BAK1, MAP3K12, and MAPK9) and proliferation-associated tumor drivers (FOS, HOXA3, and POLR2B) had an increased gene expression." (PMID 35778418, 2022). "Another study has indicated that RNF183 interacts with fetal and adult testis-expressed 1 (FATE1) in tumors and negatively regulates the apoptosis effector Bcl-2-interacting killer (BIK), leading to increased viability of tumor cells." (PMID 32486221, 2020). "Since apoptosis is oncogenic when not fully executed in cell-based models, we reasoned that BIK accelerated tumor evolution and disease relapse through failed apoptosis." (PMID 32528057, 2020). "BIK, a pro-apoptotic protein, has been reported to selectively form a complex with BiP in the tumor microenvironment." (PMID 31612867, 2019). "BIK, a member of the Bcl2 family, is a tumor suppressor, and its expression is prevented by chromosomal deletions encompassing the BIK locus or by DNA methylation in several human cancers." (PMID 27845892, 2016). "Only in poorly or well-differentiated tumor areas we found presence of BIK protein with predominant cytoplasmic location." (PMID 16060964, 2005). "Since BIK is highly expressed in maligant, we classified maligant into high BIK maligant and low BIK maligant based on the median BIK expression in maligant, The results showed a substantial increase in the proportion of high BIK maligant in tumor samples." (PMID 40438322, 2025). "Moreover, DDR1 pathway activation mediated by type I collagen inhibits tumor cell growth, through the pro-apoptotic factor BCL-2 interacting killer (BIK), a member of the BCL2 family." (PMID 39769286, 2024). "The rapid molecular evolution of LATS2 and BIK suggests that these genes may contribute to bat molecular adaptations in tumor suppression." (PMID 37728212, 2023). "BIK is a proapoptotic gene, there were research showing liposome complexed with mutant Bik(T33D/S35D) gene could enhance the anti-tumor effect of BIK in various animal cancer models, including the pancreatic cancer." (PMID 37223030, 2023). "Thus, this study identifies BIK as a biomarker for tumor recurrence of ER-positive patients and provides a potential mechanism whereby failed apoptosis contributes to cancer aggression." (PMID 32528057, 2020). "BIK is normally undetectable or expressed at low levels in cancers but specific tumors that were marked with high BIK expression have been targeted for induction of apoptosis leading to tumor reduction." (PMID 27902785, 2016). "Since E47 induced BIK in our cHL cell lines, we asked whether there is a correlation between expression levels of the two proteins in other tumor entities." (PMID 27166193, 2016).